TLR4 (toll like receptor 4)
Diseases named in the same sentence as TLR4 in open-access papers (continued):
Sharing a sentence is not in itself a finding about the gene and the disease.
tumor (continued). "RAGE and TLR4 are both implicated in S100A9-mediated tumor-associated pathological effects." (PMID 27020242, 2016). "Indeed, increased expression of TLR4 has been linked to development of inflammation-associated neoplasia." (PMID 25705893, 2015). "Furthermore, all mice vaccinated with TLR4 deficient DCs died within 30 days following tumor challenge while 60% of mice vaccinated with wild type DCs survived passed 60 days." (PMID 26336989, 2015). "TLR4 signaling might also prevent the premature lysosomal degradation of engulfed apoptotic debris and potentially preserve tumor-associated antigens for presentation." (PMID 26486085, 2015). "In addition to its response to LPS, toll-like receptor 4 can facilitate antitumor immune responses; however, emerging evidence also suggests that overactivation of this receptor is associated with tumor progression as well as tumor development." (PMID 26695753, 2015). "Patients with the loss-of-function TLR4 allele have been shown to relapse more quickly after radiotherapy or chemotherapy indicating the clinical relevance of immunoadjuvant pathway triggered by tumor cell death." (PMID 25807141, 2015). "Asp299Gly and Thr399Ile, TLR4 SNPs, are associated with tumor progression." (PMID 24959291, 2014). "Moreover, the induction of TLR4 was implicated as the molecular mechanism mediating liver damage and tumor formation in alcohol abused patients." (PMID 25177689, 2014). "TLR4 activation has been associated with apoptosis induction via various mechanisms, including activation of the pro-apoptotic function of NF-κB, modulation of tumor-suppresser expression or function etc." (PMID 24391503, 2014). "Interestingly, low expression of TLR4 was significantly associated with male patients (p = 0.045); MyD88 expression was related to the tumor site of the colon or rectum (p = 0.034)." (PMID 25547486, 2014). "Additionally, TLR4 and IL-6 expression in the tumor microenvironment were associated with the presence of adenocarcinoma, and higher levels of TLR4 expression in the tumor stroma were noted with disease progression." (PMID 23650534, 2013). "Furthermore, in UC patients with associated dysplasia or neoplasia, the level of TLR4 expression increased with dysplastic grade." (PMID 24696788, 2012). "TLR4-deficient mice display a profoundly reduced dysplasia, number and size of tumours." (PMID 20871832, 2010). "Both TLR3 and TLR4 expressions were significantly and positively associates with tumor size." (PMID 21129170, 2010). "Mutated Tlr4 caused increased inflammation in tumor-bearing mice." (PMID 19925653, 2009). "While this association between LPS and accelerated perioperative tumour growth may be a manifestation circuitous immunologically mediated singularity, a direct TLR-4 dependent effect on cancer cells may also be involved." (PMID 16892041, 2006). "Notably, TLR4 expression was significantly higher in epileptic tissues than in LGG, suggesting that elevated TLR4 may be associated with inflammatory conditions beyond tumor grade alone." (PMID 40809181, 2025). "Furthermore, innate immune responses to gut microbiota through TLR4 signaling have been implicated in gastrointestinal malignancies, with experimental evidence showing that blocking TLR4-MyD88 signaling suppresses inflammation-associated tumor development." (PMID 40703545, 2025). "Among them, the enzymes encoded by genes such as TLR4 are involved in the metabolism of endogenous and exogenous compounds, and their increased activity may lead to DNA damage, cell apoptosis, and other pro‐tumor effects." (PMID 40898658, 2025). "Among these genes, TLR4 expression exhibited the strongest positive correlation with the proportion of macrophages, particularly M2 macrophages, suggesting a potential association between TLR4 expression and a tumour microenvironment that promotes tumour progression in high‐risk patients." (PMID 40696496, 2025).
tumor (continued). "Therefore, the aim of this study was to identify the involvement of EGFR- and TLR-4-associated signaling pathways in bile duct epithelial cells during liver fluke infection-associated neoplasia in patients and animal models, as well as in a cellular model of host–parasite interactions." (PMID 40732668, 2025). "In addition, high TLR4 expression was significantly associated with larger tumor size (≥2 cm) and later clinical stage, suggesting that high TLR4 expression may be the cause of postoperative metastasis and cancer recurrence." (PMID 38463226, 2024). "Furthermore, TLR4-independent pathways, which are induced or inhibited through Sptlc2 deficiency, might potentially have contributed to the phenotype of the tumor model." (PMID 39025856, 2024). "We investigated whether clinical outcomes were associated with the tumor’s TLR4 expression." (PMID 37824131, 2023). "Among tumor-associated macrophages (TAMs), different types have been defined based on their molecular signature in vitro, with the M1 type representing the pro-inflammatory phenotype acquired after stimulation with Toll-like receptor 4 (TLR4) and interferon-γ (IFN-γ)." (PMID 38275375, 2023). "In this study, despite increasing productions of iNOS and COX-2 induced by AOM/DSS, ME pre-administration suppressed their proteins in the colon tissue of model mice, suggesting that ME could reduce chronic inflammation-associated tumor initiation by the inhibition of TLR4, NF-κB, iNOS, and COX-2." (PMID 37200915, 2023). "Finally, the presence of non-neoplastic diseases in a few study controls may impact the final results, specifically when these diseases correlate with the TLR4 polymorphism rs4986790." (PMID 36281200, 2022). "It has been reported that miR-100-5p could inhibit IL-6 and TLR4 mRNA gene expression in follicular dendritic cells during germinal center reactions, suppress inflammatory activation of microglia and promote tumor-associated macrophage M2 phenotype." (PMID 35874782, 2022). "Since we have observed that TLR4, and TLR4 expression on surrounding epithelium, may increase cell migration and invasion, further studies investigating the association of tumor recurrence and metastasis with TLR4 expression on surrounding epithelium are promising." (PMID 35327577, 2022). "Moreover, TLR4 facilitates osteoclast differentiation that may cause osteolytic destruction in the tumor surrounding area." (PMID 34588497, 2021). "Moreover, we also analyzed the mutation patterns of the TLR4 gene in tumor samples." (PMID 34631699, 2021). "The activation of the TLR4 pathway induced by H. pylori LPS markedly influences the immune response, which causes the attenuation of antitumor activity and induction of persistent infection and provides the environment to support tumor progression in gastric epithelial cells." (PMID 33217986, 2020). "In addition, TLR4 expression is associated with tumor stage." (PMID 29029545, 2017). "Fusarium species have been shown to activate the Toll-like receptor 4 (TLR4)/myeloid differentiation primary response 88 (MYD88)/NF-κB signaling pathway in tumor cells, leading to increased expression of microRNA-21 (miR-21)." (PMID 41602751, 2026). "Conversely, the Gram-negative species Nevskia ramosa showed a positive correlation with Gleason score, suggesting it likely promotes tumor progression through TLR4 activation through LPS." (PMID 41601666, 2026). "Mechanistically, macrophage-engulfed cathepsin C (CTSC) from tumor debris activates TLR4/NF-κB signaling, upregulating CXCL1/2 and complement factor B (CFB) to drive neutrophil recruitment and NET formation." (PMID 41480760, 2026). "First, the lipopolysaccharide-Toll-like receptor 4 axis sustains a chronic inflammatory loop that remodels the tumor microenvironment." (PMID 42079406, 2026).
tumor (continued). "Evidence from clinical tumour tissues, co-culture models, in vivo and in vitro studies supports the crucial interplay between TLR4 signalling and gelatinases production in tumour growth and metastasis." (PMID 42121921, 2026). "Its surface lipopolysaccharide and other virulence factors activate toll-like receptors (TLR) and inflammatory pathways in colon cells, such as inducing microRNA-21 via TLR4, resulting in chronic mucosal inflammation that supports tumor growth ​." (PMID 41486167, 2026). "Our findings indicated an inverse correlation between the expression of PD‐L1 and TLR4 (r = −0.348, p = 0.014, and r = −0.269, p = 0.049, superficial tumor site and in overall analysis, respectively)." (PMID 40762187, 2025). "In mouse models of NSCLC, cucurbitacin B effectively inhibits tumor growth and shows superior anti-tumor effects compared to standard treatments, underscoring its potential as a targeted therapy through the TLR4/NLRP3/GSDMD signaling axis." (PMID 40149884, 2025). "Fusobacterium nucleatum can activate the Toll-like Receptor 4 (TLR4) on tumor cells and initiate an intracellular signaling by Myeloid Differentiation Primary Response Protein 88 (MyD88)." (PMID 41228220, 2025). "NAMPT exists in both extracellular (eNAMPT) and intracellular (iNAMPT) forms, with eNAMPT boosting TLR4-independent macrophages activation, and iNAMPT mediating NK mitochondrial homeostasis, suggesting anti-tumor cytoxicity." (PMID 40087771, 2025). "In MC38 subcutaneous tumor models generated with TLR4 knockout mice, we further demonstrated that the enhanced antitumor immune effects of ADVNE and ADVPPE depend on the presence of the TLR4 receptor." (PMID 40082916, 2025). "TLR4 is expressed not only on immune cells but also on intestinal epithelial and tumor cells, mediating complex interactions within the tumor microenvironment." (PMID 40703545, 2025). "Two prominent changes at the cell surface that can contribute to the tumor microenvironment through auto/paracrine stimulation include increased TLR4 and increased secretion of the TLR4 agonist API5." (PMID 40878805, 2025). "The activation of the TLR4/NF - κB signaling pathway has a close correlation with tumor invasion, metastasis, and immune evasion in NSCLC." (PMID 40110044, 2025). "TLR-4 is closely linked to CRC invasion, metastasis, and poor prognosis and further participates in epithelial-mesenchymal transition and tumor microenvironment composition." (PMID 40404908, 2025). "Long non - coding RNA - NEAT1 is likely to regulate the TLR4/NF - κB signaling pathway, thereby influencing the inflammatory response within the tumor microenvironment and facilitating the tumorigenic progression." (PMID 40110044, 2025). "In HCC, HMGB1 released by tumor cells after chemoradiotherapy can be recognized by DC through TLR4, which induces DC maturation and anti-tumor immune responses." (PMID 40432108, 2025). "Intratumoural Escherichia-Shigella- and Enterobacteriaceae-derived LPS promoted NSCLC progression via the TLR4-mTOR-NF-κB-IL-6 axis, whereas the addition of the mTOR inhibitor rapamycin significantly suppressed LPS-induced tumor proliferation." (PMID 40817754, 2025). "Reconstitution of TLR4‐expressing myeloid cells in TLR4‐deficient mice restored diethylnitrosamine (DEN)‐induced hepatic inflammation and proliferation, indicating a paracrine mechanism of LPS in tumor promotion." (PMID 40314129, 2025). "In an implanted tumour mouse model of anti-PD-1 treatment, microbiota-derived hexa-acylated LPS was required for effective anti-tumour immune responses, and LPS-binding antibiotics and a small-molecule TLR4 antagonist abolished anti-PD-1 efficacy." (PMID 39929976, 2025). "We further showed that the ability of sEV‐NAMPT to promote tumour growth was dependent on TLR4 expression in recipient cells." (PMID 40237223, 2025).
tumor (continued). "Toll-like receptors (TLRs), including TLR4, play a crucial role in innate immunity activation, and small molecular TLR4 activators (agonists) are in the preclinical and clinical phases of development as vaccine adjuvants or tumor immunotherapeutics." (PMID 40124897, 2025). "A particularly significant finding was the relationship between TLR4/MyD88 activation and patterns of tumor invasion." (PMID 40703545, 2025). "FN activates the E-cadherin/β-catenin pathway and Toll-like receptor 4 (TLR4) signaling, leading to increased tumor cell proliferation." (PMID 40869155, 2025). "PSP also significantly restrained tumor expansion in a murine model of gastric cancer, likely via the suppression of the TLR4/NF-κB signaling pathway." (PMID 41293256, 2025). "In the extracellular space, it binds to toll-like receptor 4 (TLR-4) on the surface of dendritic cells to optimize the presentation of antigens from dying tumor cells." (PMID 41011719, 2025). "Lipopolysaccharide (LPS), a component of the outer membrane of Gram-negative bacteria, has been implicated in promoting tumorigenesis, with toll-like receptor 4 (TLR4) serving as its primary receptor on tumor cells." (PMID 40181829, 2025). "TLR2 and TLR4 are overexpressed in many tumor types and act as proto-oncogenes by affecting tumor cell proliferation, migration, and metastasis." (PMID 40809181, 2025). "Our study identifies distinct TLR4/MyD88 expression patterns in CRC progression and novel genetic variants associated with aggressive tumor features." (PMID 40703545, 2025). "High-fat diets also elevate free fatty acid levels, which activate toll-like receptor 4 (TLR4) signaling, further amplifying inflammation in the tumor microenvironment." (PMID 40428567, 2025). "Functional assays with the TLR4 inhibitor TAK-242 demonstrated that TLR4 blockade reversed rhENO1-induced tumor proliferation, migration, and invasion, confirming TLR4’s role in ENO1-driven malignancy." (PMID 41353343, 2025). "Overexpression of TLR-4 exacerbates tumor malignancy, whereas neutralizing antibodies targeting TLR-4 can reverse these effects." (PMID 40404908, 2025). "The data also suggest that fetuin-A in the medium can modulate the surface expression of TLR4 on tumor cells (either upregulation or downregulation) to promote adhesion, invasion and growth." (PMID 40124677, 2025). "Beyond its cytotoxic effects, Paclitaxel has shown immune-modulatory properties, specifically reprogramming TAMs from a tumor-promoting M2 phenotype to an antitumor M1 phenotype through TLR4 (Toll-like receptor 4) signaling." (PMID 40330466, 2025). "This triggers TLR signaling in the tumor cells—TLR4 and TLR9—leading to an aggressive inflammatory phenotype." (PMID 41516032, 2025). "Numerous studies have revealed that chemicals discharged by injured and deceased cells can trigger the host repair program mediated by toll-like receptor-4 (TLR-4), enhancing tumor resistance." (PMID 40404908, 2025). "In summary, the TLR4 signaling pathway, when activated by ligands such as LPS and gut microbiota metabolites, can regulate tumor cell proliferation, apoptosis, invasion, and metastasis through downstream signaling pathways such as NF-κB and MAPK." (PMID 41048488, 2025). "TLR4, p-IKKα/β, and p-IKBα protein levels in tumor tissues were markedly decreased in the YGS + cisplatin treatment group and in the Gomisin B + cisplatin treatment group (P < 0.01)." (PMID 40247422, 2025). "F. nucleatum promotes tumor progression by activating the TLR4/NF-κB pathway, directly adhering to tumor cells, increasing IL-8 production, and inhibiting ferroptosis." (PMID 40944094, 2025). "TLR4 signaling operates through both myeloid differentiation factor 88 (MyD88)-dependent and independent pathways, potentially promoting tumor progression by enhancing tumor cell adhesion, invasion, and metastasis via NF-κB regulation." (PMID 40703545, 2025).
tumor (continued). "The MSC1 phenotype, a pro-inflammatory, tumor-suppressive state induced by short-term, low-dose LPS activation via TLR4, has shown therapeutic promise but remains poorly characterized in CRC." (PMID 40564222, 2025). "Our findings demonstrate that enhanced TLR4/MyD88 signaling significantly correlates with aggressive tumor features, particularly perineural invasion (p=0.029) and tumor budding (p=0.022)." (PMID 40703545, 2025). "At the same time, NETs can also directly contact naïve CD4+ T cells through TLR4, promote Treg cell differentiation, inhibit the immune properties of T cells, promote immune escape, and ultimately lead to tumor drug resistance." (PMID 40979214, 2025). "This article reviews the critical role of TLR-4 and its signaling pathways in inducing chemotherapy resistance in tumor cells." (PMID 40404908, 2025). "During tumor development, TLR4 activation promotes the production of proinflammatory chemokines and immunosuppressive cytokines in an unregulated manner." (PMID 40143078, 2025). "Previous studies have reported similar self-amplifying loops between HMGB1 and TLR4 in other malignancies, where sustained activation of this axis enhances tumor aggressiveness." (PMID 40559922, 2025). "Then, neutrophil elastase released by NETs activates TLR4 on tumor cells, leading to the upregulation of PGC1α, enhanced mitochondrial biogenesis, and accelerated tumor cell proliferation." (PMID 40092983, 2025). "Patients with very high levels of TLR-4 in the tumor stroma relapsed significantly earlier than those with lower expression levels." (PMID 41465346, 2025). "This property ensures that NPs are preserved intact in normal tissues but rapidly dissociate into monomers in acidic tumor tissues, rapidly releasing agonists to activate the TLR4 and STING pathways efficiently." (PMID 40486836, 2025). "The clinical application of the TLR4 gene in AK and cSCC involves understanding its role in tumor progression and immune response modulation." (PMID 39925808, 2025). "Extensive studies using GI cancer models have revealed that AMK compounds, especially ATL-1 and ATL-3, inhibit tumor growth through the TLR4/MyD88 pathways and mitochondrial signaling." (PMID 40144663, 2025). "In summary, TLR4 mediates increased neutrophils and inhibition of tumor growth in the presence of CS1." (PMID 40592236, 2025). "The tumor markers, inflammatory factor, mRNA and protein expression of TLR4/NF-κB/NLRP3 inflammasome related indicators in serum and esophageal tissue was determined by ELISA, qPCR, and western blot (WB) respectively." (PMID 40606986, 2025). "Reflecting its context-dependent immunobiology, LPS exerts dual immunosuppressive and immunostimulatory effects in tumor immunity, unified by its core engagement of the TLR4 pathway." (PMID 41181090, 2025). "This gap in the literature is significant, given the well-documented role of TLR4 in mediating tumor progression." (PMID 41332426, 2025). "The role of TLR4 in recruiting TAMs into the tumor microenvironment, as evidenced in TLR4-null mice and the correlation between TLR4 and TAMs in human cancers, supports the role of TLR4 in cancer treatment." (PMID 40878805, 2025). "When TLR-4 is abnormally expressed in tumor cells, it can be activated directly by paclitaxel or indirectly by other chemotherapeutic drugs." (PMID 40404908, 2025). "In combination with the TLR4 agonist, the circGPC3 vaccine effectively suppressed tumor progression in subcutaneous and orthotopic tumor mouse models, and showed a favorable safety profile with no apparent evidence of tissue damage." (PMID 41445747, 2025). "Although an increased expression of ICD-related molecules is observed in vitro, we observe that the tumor growth of Cdk2-/- cells with increased HMGB1 release in Tlr4-/- mice remained similar to that in C57 mice." (PMID 40557162, 2025).